ENPP1 (ectonucleotide pyrophosphatase/phosphodiesterase 1)
Diseases named in the same sentence as ENPP1 in open-access papers (continued):
Sharing a sentence is not in itself a finding about the gene and the disease.
tympanosclerosis (1 paper, 2016). The formation of dense connective tissue in the tympanic membrane that does not necessarily cause or lead to loss of hearing. "Other abnormalities observed in the Enpp1 mutant mice include over-ossification at the round window ridge, thickened and over-calcified stapedial artery, fusion of malleus and incus, and white patches on the inside of tympanic membrane, some of which are typical symptoms of tympanosclerosis." (PMID 27959908, 2016).
tumor (73 papers, 2010 to 2026). "Another promising target is ectonucleotide pyrophosphatase/phosphodiesterase 1 (ENPP1), frequently overexpressed in a variety of malignancies and closely associated with the formation of an immunosuppressive tumor microenvironment." (PMID 41200171, 2025). "Recent reports have also suggested that the loss of ENPP1 function in both cancer cells and normal tissues resulted in a reduced primary tumor initiation and growth." (PMID 39318624, 2024). "This reagent will help to decipher the function of ENPP1 in the regulation of the immune response, allow a quick identification of ENPP1-deficiency and of ENPP1-positive tumors, and constitutes the basis for targeted anti-tumor intervention." (PMID 39694917, 2024). "ENPP1 loss-of-function in both cancer cells and normal tissues slowed primary tumor growth and abolished metastasis." (PMID 38117852, 2023). "Together, our data draw a connection between enhanced extracellular cGAMP signaling and immunological control of primary tumor growth upon Enpp1 loss." (PMID 38117852, 2023). "Overall, both ENPP1’s physiological importance and its association with aggressive cancer make it an important target for the development of anti-tumor therapeutics." (PMID 36761762, 2023). "In this model, loss of ENPP1 in the tumor inhibited metastasis and restored immune infiltration and sensitivity to treatment with immune checkpoint inhibitors, which required cGAS in the tumor cells and STING in the host cells." (PMID 37287967, 2023). "Taken together, these results indicate that ENPP1 expression is induced during anchorage-dependent growth and is associated with tumour formation." (PMID 26065921, 2015). "Specifically, decreased expression of TANK and ENPP1—both associated with immune evasion and tumor progression—suggests that SKD may attenuate immunosuppressive pathways in these cells." (PMID 41301480, 2025). "Interestingly, loss of ENPP1 function suppressed metastasis, restored immune infiltration in the tumor microenvironment, and synergized with immune checkpoint inhibition in a cGAS-STING-dependent manner." (PMID 38095464, 2024). "Furthermore, inhibition of the 2′3′-cGAMP hydrolase ENPP1 was reported to enhance export and accumulation in the media both at steady state and following DNA damage, promoting tumor associated immune infiltration." (PMID 33013881, 2020). "As ENPP1 expression is much higher on 293T-ENPP1 than HepG2 cells, we hypothesize that the underlying mechanism targeting tumor cells is different from that of non-tumor (isogenic 293T) cells." (PMID 36761762, 2023). "Tumors that overexpress ENPP1 and rapidly degrade cGAMP avoid immune surveillance in the tumor microenvironment and are highly resistant to cancer immunotherapy." (PMID 42055331, 2026). "Since ENPP1 expression has been reported to be a predictive factor in many tumor types, we included it as a covariate." (PMID 41496120, 2026). "A key resistance mechanism involves tumor-derived exosomes carrying ENPP1, which hydrolyzes extracellular cGAMP - including LL-37-bound cGAMP - thereby suppressing STING activation in immune cells and inhibiting T cell infiltration." (PMID 41573551, 2025). "The high expression of ENPP1 in these exosomes facilitated immune evasion, potentially impacting tumor growth and metastasis." (PMID 40103824, 2025). "We demonstrate in preclinical models the efficacy of a novel Enpp1 inhibitor and show that this inhibitor improves tumor control by radiation even where the cancer cells lack Enpp1." (PMID 39622844, 2024). "This suggests that tumors secrete ENPP1‐positive exosomes to promote immune evasion by hydrolysis of 2′3′‐cGAMP and transporter‐2′3′‐cGAMP in the tumor microenvironment." (PMID 38498770, 2024). "A poster presentation provided preliminary results showing that the orally administered ENPP1 inhibitor, MV-626, acted synergistically with radiation treatment, resulting in tumor eradication in the six mice tested." (PMID 38659582, 2024).
tumor (continued). "This demonstrates the important role of tumor exosomal ENPP1 in inhibiting the cGAS‐STING signaling pathway." (PMID 38498770, 2024). "ENPP1 was shown to promote immune evasion and tumor metastasis following hydrolysis of cGAMP, further substantiating its pro-tumoral role." (PMID 38095464, 2024). "Our results also raise the possibility that disrupting hydrolytic activity of tumor exosomal ENPP1 in ENPP1 blocking therapy is a previously unrecognized mechanism in cGAS‐STING pathway." (PMID 38498770, 2024). "By inhibiting this pathway, ENPP1 can promote tumor growth and metastasis, and can therefore be used as a stratification biomarker and target for immunotherapy." (PMID 39694917, 2024). "Overall, our study reveals a mechanism by which tumor exosomal ENPP1 inhibits cGAS‐STING signaling through the hydrolysis of 2′3′‐cGAMP." (PMID 38498770, 2024). "We observed that many human and murine cancer cells lack Enpp1 expression, but that Enpp1 is expressed in cells of the tumor stroma where it limits tumor control by radiation therapy." (PMID 39622844, 2024). "When incubating with tumor‐derived exosomes with high expression of ENPP1, 2′3′‐cGAMP was degraded rapidly and completely degraded at 4 h." (PMID 38498770, 2024). "We found not only that exosomes derived from various tumor cells express ENPP1 protein, but also that ENPP1 is abundantly enriched on exosomes." (PMID 38498770, 2024). "In summary, these results demonstrate that tumor exosomal ENPP1‐mediated extracellular 2′3′‐cGAMP hydrolysis inhibits cGAS‐STING signaling in bystander cells." (PMID 38498770, 2024). "Enhancing local anti-tumor immunity by targeting ENPP1 significantly reduces systemic toxicity resulting from excessive cGAMP degradation." (PMID 39420203, 2024). "The extracellular 2′3′‐cGAMP level was higher in the co‐culture system with STF‐1623 treatment than that without STF‐1623 treatment, which indicates that the cGAMP hydrolase activity of tumor exosomal ENPP1 was blocked by STF‐1623." (PMID 38498770, 2024). "Collectively, these findings complement the results of our previous in vitro experiments and further demonstrate the important role of tumor exosomal ENPP1 in cancer." (PMID 38498770, 2024). "To test the role of tumor exosomal ENPP1 in the tumor immune microenvironment, we investigated the regulation of tumor exosomal ENPP1 on immune response induced by endogenous 2′3′‐cGAMP in a co‐culture system of tumor cells and immune cells." (PMID 38498770, 2024). "By examining the innate immune regulation function of tumor‐derived exosomes in vitro, we further elucidated the role of ENPP1 in a broader clinical setting." (PMID 38498770, 2024). "This highlights the important role of tumor‐derived exosomes in the innate immune response and deepens our understanding of the ENPP1‐mediated cGAS‐STING pathway." (PMID 38498770, 2024). "ENPP1 proteins are secreted by various tumor cells to the extracellular space via the exosomes and ENPP1 highly enriched in these exosomes." (PMID 38498770, 2024). "By cGAMP degradation in combination with AMP generation, the substrate for the production of immunosuppressive adenosine, ENPP1 expressed on tumor cells enhances tumor growth by reducing both the innate and adaptive anti-cancer responses." (PMID 39694917, 2024). "In summary, our study identifies a new molecular mechanism for tumor immune evasion by tumor exosomal ENPP1." (PMID 38498770, 2024). "While inhibition of Enpp1 regulates a range of gene pathways in tumors, radiation has a dominant impact on gene expression in the tumor immune environment, including increased activation of IFN-regulated gene pathways." (PMID 39622844, 2024). "Collectively, based on the results of our extensive in vitro experiments, tumor exosomal ENPP1 definitely plays a crucial role in the regulation of cGAS‐STING signaling pathway." (PMID 38498770, 2024).
tumor (continued). "To validate the importance of innate sensing and IFN response mechanisms of tumor control by Enpp1 inhibition combined with radiation therapy, we compared radiation therapy and VIR3 treatment in MC38 tumors grown in wild-type C57BL/6 mice." (PMID 39622844, 2024). "Against this backdrop, we report herein that various tumor cell‐derived exosomes carry ENPP1 proteins; indeed, ENPP1 is highly enriched in these exosomes." (PMID 38498770, 2024). "Together, these data demonstrate that treatment with RT and VIR3 to inhibit Enpp1 results in tumor control via an immune mechanism that is dependent on STING signaling in host cells and type I IFN responses in host cells." (PMID 39622844, 2024). "Alternatively, ENPP1 inhibition has much more potential to exert a significant anti-tumor activity with reduced autoimmune related toxicity concerns." (PMID 39318624, 2024). "Inhibition of ENPP1 function slows tumor growth, prevents metastasis, and selectively blocks the cGAMP hydrolysis function of ENPP1, replicating the effects of complete ENPP1 knockout." (PMID 39185402, 2024). "In the study described herein, we reveal a new mechanism by which tumor exosomal ENPP1 can hydrolyze 2′3′‐cGAMP effectively to inhibit cGAS‐STING pathway activation in immune cells." (PMID 38498770, 2024). "We next sought to directly link the tumor exosomal ENPP1 and cGAS‐STING signaling by introducing GW4869, an inhibitor of exosome synthesis and secretion, into a co‐culture system." (PMID 38498770, 2024). "Collectively, all results verified that tumor exosomal ENPP1 plays an important role in the hydrolysis 2′3′‐cGAMP bound to LL‐37 to inhibit cGAS‐STING signaling." (PMID 38498770, 2024). "To profile Enpp1 expression in cell populations infiltrating murine tumors, we analyzed a scRNASeq dataset of six murine tumor models." (PMID 39622844, 2024). "Small-molecule inhibitors of ENPP1 have set therapeutic precedent for blocking the hydrolysis of endogenous cGAMP in the TME to sensitize tumor cells to immunotherapy and radiation." (PMID 37400538, 2024). "At the end of our project, we sought to explore the role of tumor exosomal ENPP1 in human cancers by analyzing various tumor tissues." (PMID 38498770, 2024). "Strikingly, the Western blot expression intensity of tumor exosomal ENPP1 also shown an inverse correlation with CD8+ T cells and CD4+ T cells infiltration, respectively." (PMID 38498770, 2024). "Using a novel Enpp1 inhibitor that can be delivered orally and results in on-target inhibition of Enpp1 activity in mice, we demonstrate that Enpp1-targeted therapy improves tumor control by radiation therapy in these cancers." (PMID 39622844, 2024). "We observed that tumor exosomal ENPP1 can hydrolyze 2′3′‐cGAMP to inhibit cGAS‐STING signaling, regardless of the concentration of exosomes." (PMID 38498770, 2024). "In vivo, tumor cells probably secrete ENPP1‐positive exosomes to accelerate the hydrolysis of extracellular 2′3′‐cGAMP and LL‐37‐2′3′‐cGAMP, which promotes tumor immune evasion." (PMID 38498770, 2024). "Herein, it is reported that various tumor‐derived exosomes carry ENPP1, and can hydrolyze synthetic 2′3′‐cGAMP and endogenous 2′3′‐cGAMP produced by cells to inhibit cGAS‐STING pathway in immune cells." (PMID 38498770, 2024). "To examine the interaction of tumor exosomal ENPP1 and LL‐37‐2′3′‐cGAMP, we obtained exosomes from ENPP1‐eGFP‐overexpressed cells (A375 ENPP1‐eGFP EXOs)." (PMID 38498770, 2024). "One important consideration is that ENPP1 is also expressed in some normal tissues; therefore, potential off-tumor toxicities of anti-ENPP1 immunotherapies will require investigation." (PMID 37400538, 2024). "Collectively, these results verify that various tumor‐derived exosomes carried ENPP1 proteins, and tumor exsomal ENPP1 can hydrolyze 2′3′‐cGAMP and LL‐37‐2′3′‐cGAMP." (PMID 38498770, 2024).
tumor (continued). "The cGAMP released from cancer cells can be degraded by ENPP1 present in the microenvironment, limiting the relative contribution of cGAMP from the tumor cells." (PMID 38659582, 2024). "Since secreted cGAMP activates the immune system to reduce tumor growth and spreading, extending the lifespan of extracellular cGAMP by targeting ENPP1 is a therapeutic strategy." (PMID 39295301, 2024). "ENPP1 promotes an immunosuppressive tumor microenvironment by the imbalance of ATP/adenosine and impairs the STING (stimulator of interferon genes) pathway immune response by the hydrolysis of the effector cGMP–AMP." (PMID 38254798, 2024). "In summary, our work reveals a new mechanism by which tumor cells can secrete exosomes that carry ENPP1 to effectively hydrolyze 2′3′‐cGAMP and LL‐37‐2′3′‐cGAMP in the tumor microenvironment and, therefore, inhibit the cGAS‐STING pathway in immune cells." (PMID 38498770, 2024). "Several reports have shown that cotreating small-molecule ENPP1 inhibitors with an immune checkpoint blockade substantially enhances tumor regression." (PMID 37400538, 2024). "While WT had slower primary tumor growth as Sting1−/−mice, the two genotypes had similar lung metastatic burden, indicating that endogenous ENPP1 activity in the tissue fully blocks STING-mediated immunological protection specifically against metastasis." (PMID 38117852, 2023). "Unexpectedly, overexpression of WT ENPP1 resulted in a dramatic decrease in tumor-infiltrating naive B cells in both the primary and metastatic TME compared with the catalytic mutant." (PMID 38117852, 2023). "Overall, ENPP1 potently suppresses the proinflammatory effects of extracellular cGAMP within the tumor microenvironment." (PMID 37287967, 2023). "Enpp1H362Amice retarded E0771 tumor growth to a similar degree as Enpp1−/− mice, as compared to WT mice and the tumor slowing effects in Enpp1H362A mice were completely abolished in the Sting1 knockout background." (PMID 38117852, 2023). "Another way of triggering STING responses in the tumor-microenvironment while by-passing ENPP1 degradation is to use the recently developed modified CDNs that are resistant to ENPP1 degradation." (PMID 37287967, 2023). "Together, our data suggest a model in which ENPP1 overexpression promotes primary tumor growth and metastasis through synergistic stimulation of the eADO pathway and inhibition of the STING pathway." (PMID 38117852, 2023). "Characterization on tumor cells with different ENPP1 expression levels and comparison with an irrelevant ADC as a negative control is needed to better understand this phenomenon." (PMID 36761762, 2023). "This trend suggests that Enpp1 knockout slows primary tumor growth at least partially through enhancing extracellular cGAMP levels." (PMID 38117852, 2023). "For example, in a breast cancer model, ENPP1 overexpression led to enhanced tumor metastasis in the bone." (PMID 38022587, 2023). "Our results support a model in which both tissue-derived and tumor-derived ENPP1 act in concert to promote primary tumor growth and distal organ metastasis." (PMID 38117852, 2023). "Upregulation of ENPP1 also correlates with resistance to immunotherapy and reduction of immune cell infiltration to tumor sites." (PMID 36761762, 2023). "ENPP1’s contribution to different stages of tumor development including initiation, progression, and metastasis was not well understood." (PMID 38117852, 2023). "Together, these data support the utility of targeting ENPP1 expressing tumor cells with ENPP1-specific CAR T cells." (PMID 36761762, 2023). "On day 15, we observed a near 75% reduction in average tumor sizes upon Enpp1 deletion: an effect that was around 50% rescued with extracellular cGAMP neutralization but not with the NB STING treatment." (PMID 38117852, 2023). "In accord, Enpp1-/- mice unable to degrade cGAMP are resistant to tumor development in multiple models of cancer." (PMID 37287967, 2023).